PLG (plasminogen)
Diseases named in the same sentence as PLG in open-access papers (continued):
Sharing a sentence is not in itself a finding about the gene and the disease.
COVID-19 (continued). "When bleeding emerges in severe COVID-19 patients, measurement of PT, APTT, fibrinogen, FDP, D-dimer, AT, TAT, PIC, plasminogen, and αPI2 represents the first step toward appropriate differentiation." (PMID 35328761, 2022). "Since the mortality in COVID-19 patients increases in logarithmic way and comorbidities and older age have a great impact on it, we aimed to evaluate whether factors, such as alteration in plasminogen levels, that generate the “blood clots storm” may be predictive markers." (PMID 34354045, 2021). "Numerous studies aimed at establishing T-PA, which activates plasminogen to plasmin, as well as PAI-1, which acts as an upstream inhibitor of T-PA, as potential pathognomonic analytes with regard to COVID-19 disease severity." (PMID 33564744, 2021). "Taken together, these data suggest a potential relationship between levels of inflammation, mediated by IL-6, levels of circulating plasminogen, as marker of fibrinolysis, and the shorter time in forming clots, as per APTT levels, typical of COVID-19 patients." (PMID 34354045, 2021). "According to our findings, among patients with moderate/severe COVID-19, besides decreased FVIII activity, higher CRP levels, prolonged APTT, decreased functional plasminogen activity, and markedly reduced FXIII levels were observed compared to those with asymptomatic/mild disease." (PMID 40303405, 2025). "Our study found increased antithrombin and plasminogen in pre-COVID-19 dengue patients, but not TFPI, compared to post-COVID-19 patients and controls." (PMID 41305453, 2025). "In another study, fibrinogen, tPA, and PAI-1, but not plasminogen levels, were elevated in patients with severe COVID-19." (PMID 37175942, 2023). "Low levels of plasminogen were found in severe COVID-19 patients and therefore proposed as a negative prognostic factor in COVID-19." (PMID 37569751, 2023). "In patients with COVID-19, impaired fibrinolysis is secondary to high plasminogen activator inhibitor 1 (PAI-1) levels, a member of the serine protease inhibitor superfamily that blocks the conversion of precursor plasminogen to active plasmin." (PMID 36979908, 2023). "The potential of plasminogen as a life-saving treatment for non-resolving post-COVID-19 pulmonary fibrosis warrants further investigation." (PMID 36674896, 2023). "In contrast, the plasma level of plasminogen, but not alpha-2-antiplasmin, was significantly lower among COVID-19 patients with thrombocytopenia (<150 g/L) than in patients with normal platelet counts (>150 g/L)." (PMID 34940584, 2021). "As plasminogen and plasmin can serve as a complement inhibitor and C5 convertase, respectively, the PLAT Alu I/D could also affect complement activation in COVID-19." (PMID 33390179, 2021). "On the other hand, treatment by inhalation of fibrinolysis-related substances, such as tPA and plasminogen, can be administered at any stage of COVID-19 without concerns about bleeding." (PMID 32959003, 2020). "Similarly, circulating PLG levels were comparable in COVID-19 patients and healthy controls, as well as in non-ICU and ICU COVID-19 patients." (PMID 38791043, 2024). "The most likely assumption is that the increase in D-dimer levels in COVID-19 patients is due to local, extravascular activity of the fibrinolytic system in the lungs and may not reflect the degree of activation of plasminogen and fibrinolysis occurring in tissues." (PMID 39457048, 2024). "In patients with COVID-19 and PPH APTT was significantly prolonged and plasminogen levels were significantly lower as compared to women without PPH, with or without COVID-19." (PMID 40303405, 2025). "Interestingly, only IL-6 showed significant correlation with markers of fibrinolysis in the COVID-19+ group, including a significant negative correlation with FXIII-B and with plasminogen levels and a moderate, significantly positive correlation with D-dimer." (PMID 40303405, 2025).
breast carcinoma (40 papers, 1997 to 2025). "Additionally, PLG has been implicated in the development and progression of several malignancies, including lung cancer, breast cancer, colorectal cancer, and meningiomas." (PMID 40821775, 2025). "The plasminogen activation system is critical for the dissolution of fibrin clots, plays a major role in processes of tissue remodeling and cell migration, and has been compellingly implicated in the biology of breast cancer." (PMID 35454092, 2022). "In addition, more recent studies in human and mouse mammary cancer cells have found that dDAVP can induce anti-angiogenic effects associated with the proteolytic conversion of plasminogen to angiostatin." (PMID 26306290, 2015). "Treating these breast cancer cells with this antibody led to a decrease in invasiveness due to inhibited plasminogen activation; plasminogen is critical for invasion, as it degrades the extracellular matrix." (PMID 39766058, 2024). "Our in silico analysis explains the manifestation of significantly lower survival in patients with breast cancers with high levels of plasminogen protein." (PMID 38595825, 2024). "The interaction of plasminogen with cancer cells plays a key role in progression of breast cancer and other cancers." (PMID 35454092, 2022). "Most recently, Ranson showed that viable MDA-MB-231 breast cancer cells bind plasminogen with moderate affinity and high capacity (Kd of 1.8 μM, and 5.0 × 107 receptor sites per cell)." (PMID 34944416, 2021). "Bradykinin, for example, can have its availability affected negatively by metalloproteinases, while the inhibition of plasminogen activation attenuates the metastatic behavior of breast cancer cells." (PMID 33381445, 2020). "Among these SeCEP genes, CLEC3A is a C-type lectin that promotes tumor adhesion in breast cancer and was recently found to enhance plasminogen activation by tissue-type plasminogen activator." (PMID 31146747, 2019). "In this study, we retrospectively evaluated the relationship between and the potential interaction of uPA and PAI-1, which are two members of the plasminogen/plasmin system, and the occurrence of dCK + cells in in a cohort of 481 breast cancer cases." (PMID 31307406, 2019). "For example, two MAbs directed against the VKIALEVEIATY K8 motif led to unveiling the role of K8 in the plasminogen–uPA system in breast cancer." (PMID 30453567, 2018). "Using a 3D collagen I assay, myofibroblasts were shown to direct breast cancer cell motility in a plasminogen-dependent manner." (PMID 28506312, 2017). "V2R-expressing breast cancer cells are stimulated by dDAVP to secrete plasminogen activators such as urokinase, thus excising angiostatin from plasminogen." (PMID 26306290, 2015). "Our finding are consistent with previous reports that have shown annexin A2 neutralizing antibodies to inhibit cell migration, invasion, and to block plasminogen activation of breast cancer cells and monocytes in vitro." (PMID 23945256, 2013). "Breast cancer cells secrete a variety of matrix metalloproteinases (MMPs) and active plasminogen, which hydrolyses ECM and facilitates tumor invasion and metastasis." (PMID 23497249, 2013). "It has been shown that uPA expression is enhanced in many malignant tumors, such as breast cancer, prostate cancer, colon cancer, stomach cancer and lung cancer, and its mediated-plasminogen activation is dependent on its receptor uPAR in cells." (PMID 21798065, 2011). "While the physiological role of PAI-1 is to inhibit plasminogen activation, it is a poor prognostic indicator for a number of cancers, including breast cancer." (PMID 19672469, 2009). "Previous studies focused on messengers of the components of the plasminogen activation system in human breast cancer by mainly comparing normal, benign and malignant breast tissues or by examining the cellular localization of uPA and PAI-1." (PMID 16945123, 2006).
breast carcinoma (continued). "In accordance with this finding, the breast cancer cells degraded collagen under serum-free conditions only when supplemented by exogenous plasminogen." (PMID 15701164, 2005). "The urokinase-dependent activation of plasminogen by breast cancer cells plays an important role in metastasis." (PMID 11556845, 2001). "Mechanistically, Plg-RKT may regulate breast cancer progression by binding plasminogen on cancer cell surfaces to promote its activation to plasmin, leading to fibrinolysis, extracellular matrix degradation and activation of proenzymes of MMPs." (PMID 35454092, 2022). "Specifically, S100A10 in a heterotetramer with Annexin II can act as co-receptor for tPA, plasminogen and pro-cathepsin B to promote invasion and metastasis in breast carcinoma and glioma cells, but it can also affect macrophage invasion and breast cancer cell proliferation." (PMID 33809973, 2021). "We showed that TAFI can inhibit plasminogen activation on the breast cancer cell surface." (PMID 27221823, 2016). "Therefore, our results also demonstrated that inhibition of ανβ6 expression in breast cancer MCF-7 cells suppresses the plasminogen-dependent degradation of the extracellular matrix." (PMID 25176506, 2014). "The existence of a proteolytic positive feedback loop in plasminogen activation has profound implications for the ability of breast cancer cells expressing high amounts of uPA to accumulate a large proteolytic capacity at the cell surface, thereby conferring invasive potential." (PMID 17257442, 2007). "However, the possibility of other known MMPs also being involved in plasminogen-dependent collagenolysis by breast cancer cells cannot be excluded." (PMID 15701164, 2005). "These in vitro observations suggest that combinations of proteinase inhibitors, particularly of uPA/plasminogen activation and MMPs, may merit clinical evaluation as potential antimetastatic therapy for breast cancer." (PMID 9083329, 1997). "Furthermore, eK8 was shown to interfere with the plasminogen/tissue-type plasminogen activator system and to participate in the Plg-dependent activation of matrix metalloproteinases during the invasion process in breast cancer." (PMID 30453567, 2018). "Doxorubicin (1 μM) was found to significantly stimulate the expression of PLG (plasminogen, downregulated by Twist1 inhibitors; ANGPT2 (involved in breast cancer metastasis in brain); IGF-1 (a stimulator of TWIST1) and GLI1 (activated upon TWIST1 activation)." (PMID 31331001, 2019). "Taken together, these results indicate a vital role for TAFIa in regulating pericellular plasminogen activation and ultimately ECM proteolysis in the breast cancer microenvironment." (PMID 27221823, 2016). "In addition, expression of maspin reduces metastasis of breast cancer cells via repressing urokinase plasminogen activator (uPA)/urokinase plasminogen activator receptor (uPAR) complex, which enhances the cleavage of a number of extracellular matrix proteins through activating plasminogen." (PMID 26296971, 2015). "Urokinase-type plasminogen activator (uPA) receptor, which lies on the surface of breast cancer cells, combines with free uPA in ECM and converts more plasminogen into plasmin." (PMID 23497249, 2013). "Interestingly, the depletion of plasminogen from serum also completely blocked breast cancer cell mediated collagen dissolution, implicating the PAS in breast cancer-mediated collagen degradation." (PMID 15701164, 2005). "In contrast, the TGFβ-stimulated breast cancer cell lines achieved a minimal amount of degradation of either matrix in the absence of plasminogen." (PMID 15701164, 2005). "Another study showed that both WT and plasminogen-null mice carrying the Polyoma middle T antigen under the control of the mouse mammary tumor virus long terminal repeat uniformly developed multiple bilateral mammary tumors that were indistinguishable." (PMID 22185818, 2011).
breast carcinoma (continued). "We have previously shown that the metastatic breast cancer cell line MDA-MB-231 over-expresses urokinase and binds and efficiently activates plasminogen at the cell surface compared to non-metastatic cells." (PMID 11556845, 2001). "In contrast, exposure of collagen to untreated and pSUPER-control-treated human breast cancer MCF-7 cells in the presence of exogenous plasminogen significantly increased the basal level of collagen type IV degradation, compared to the corresponding control cells in the absence of plasminogen." (PMID 25176506, 2014).
Stroke (29 papers, 2009 to 2025). Sudden impairment of blood flow to a part of the brain due to occlusion or rupture of an artery to the brain. "Univariate analysis revealed that low CBS, higher NIHSS at admission, history of previous stroke, and higher plasminogen at admission were significantly associated with poor short-term outcome." (PMID 34234378, 2021). "tPA breaks down blood clots by catalyzing the conversion of plasminogen to plasmin and is used as a thrombolytic agent in the early stages of stroke." (PMID 39001884, 2024). "In contrast, plasminogen levels negatively correlated with brain injury when measured after thrombolysis with tPA after stroke." (PMID 37511788, 2023). "Another protein that can be produced by plants is tissue plasminogen activator, a protein that converts plasminogen to plasmin—which is then followed by blood clot lysis—providing a valuable treatment for stroke patients." (PMID 35164060, 2022). "A treatment that has been demonstrated to reduce brain damage after stroke is tissue plasminogen activator (t-PA), an enzyme which converts plasminogen to plasmin that dissolves emboli and thrombi, thereby restoring CBF." (PMID 33348090, 2021). "Most studies focus on targeting the biological factors related to disease pathogenesis, e.g. use of recombinant activator of plasminogen in the treatment of stroke." (PMID 34390472, 2021). "In another study, low levels of SERPINA1, PLG, KLKB1, ITIH4, and APOL1 in serum of patients with lacunar stroke were associated with poor prognosis and increased risk of recurrent stroke or myocardial infarction and cognitive decline." (PMID 31242583, 2019). "Recombinant annexin A2 increases the catalytic efficiency of rt-PA in converting plasminogen to plasmin and enhances the thrombolysis efficacy of rt-PA, with improvement of neurological outcome in a rat model of stroke." (PMID 29232823, 2017). "This is particularly relevant because intravenous tissue plasminogen activator (tPA), which cleaves fibrin by generating plasmin from its precursor plasminogen, remains the only approved pharmacologic treatment for stroke patients." (PMID 28700732, 2017). "Our data suggest that plasminogen-dependent proteolysis has a beneficial effect during neurological recovery after stroke, at least in part, by promoting axonal remodeling in the denervated spinal cord." (PMID 24732409, 2014). "Several components of the plasminogen activation cascade have been found to be involved in CNS pathologies, including stroke, TBI, MS, and EAE." (PMID 24120085, 2013). "In particular, the therapeutic effects of the small molecule Stachybotrys microspora triprenyl phenol-7 (SMTP-7), that promotes activation of plasminogen through the modulation of plasminogen conformation, against cerebral ischemia has been tested in several rodent models of stroke." (PMID 29438357, 2018). "However, additional study is required to evaluate the efficacy and safety of plasminogen activators as a treatment for stroke among COPD patients." (PMID 29723340, 2018). "Since plasminogen/plasmin activity also plays a role in thrombotic diseases, we tested if the G-allele at PLG-rs145535174 increases the risk of myocardial infarction (MI), stroke, or venous thromboembolism (VTE) in the UK Biobank." (PMID 28787443, 2017). "Despite the unquestionable beneficial tPA effects in clinical studies, animal studies revealed that endogenously produced or exogenously administered tPA has multiple roles in stroke pathology including plasminogen dependent beneficial and plasminogen dependent and independent deleterious effects." (PMID 23658802, 2013). "Actually, the main treatment against stroke is thrombolysis with recombinant plasminogen." (PMID 23843951, 2013). "Interestingly, plasminogen activity also showed a significant, step-wise negative association with stroke severity in this cohort- the biological relevance of which needs to be investigated in further studies." (PMID 34135389, 2021).
Stroke (continued). "Based on our data, we suggest that CPN2, FXII, PLG, MASP1, APCS, PON1, and CA1 for IS and FBLN1 and GRN for ICH should be further scientifically pursued as potential stroke blood biomarkers." (PMID 34975707, 2021). "Based on the logistic regression model including age, sex, previous stroke, NIHSS on admission, plasminogen activity on admission, and CBS, only age, NIHSS on admission and CBS were identified as independent predictors of poor short-term outcome." (PMID 34234378, 2021). "KD025 was more potent than fasudil in attenuation of rt-PA- and plasminogen-induced BBB permeation under normoxia, but especially under stroke-like conditions." (PMID 28510599, 2017). "While fibrinogen levels did not suggest extensive consumption related to stroke severity, interestingly, plasminogen activity showed a significant step-wise decrease in case of more severe strokes." (PMID 34135389, 2021). "Hence, it is not likely to be obviously assumed that brain-derived plasminogen is activated at the BBB during stroke by endogenous t-PA." (PMID 26834557, 2016).